EPCAM (epithelial cell adhesion molecule)
Diseases named in the same sentence as EPCAM in open-access papers (continued):
Sharing a sentence is not in itself a finding about the gene and the disease.
ovarian carcinoma (continued). "On the other hand, ATM and PALB2 are considered moderate penetrance genes in breast and ovarian cancer, and MSH6, PMS2, and EPCAM are considered moderate penetrance genes in LS CRC." (PMID 38201484, 2023). "Using nPLEX and ascites samples from ovarian cancer patients, the authors identified exosomal CD24 and EpCAM as biomarkers for ovarian cancer diagnostics." (PMID 36770486, 2023). "It was found that expression levels of EpCAM and CD24 of CD63+ sEVs were significantly higher in ovarian cancer patients compared with healthy controls." (PMID 37504087, 2023). "We analyzed two ovarian cancer cell lines MES-OV and SK-OV-3 and clinical samples from patients with ovarian cancer with different histological types and grades to study the correlation between CD117/EpCam abundance and aggressiveness of the tumors." (PMID 36875773, 2023). "In human epithelial ovarian cancers, EGF was found to hinder cell migration by upregulating EpCAM and activating ERK1/2 signaling." (PMID 36369033, 2022). "Data have also shown that EpCAM and CD44 are highly expressed in ascites exosomes, serving as a theoretical and experimental basis for the application of exosomes in ovarian cancer immunotherapy." (PMID 36741380, 2022). "An antibody functionalized microfluidic platform was reported for the detection of biomarkers that exist in the membranes of cancer exosomes, i.e. EpCAM, CD9, in order to dissociate exosomes from ovarian cancer serum." (PMID 36259505, 2022). "al used immunomagnetic bead screening, targeting epithelial markers EpCAM, HER2, and MUC1 on ovarian cancer cells, combined with multiplex RT-qPCR analysis of isolated mRNA from CTCs and tumour tissues for detecting CTCs in 109 EOC patients." (PMID 35545786, 2022). "The binding specificity of [99mTc]Tc-labeled Ec1-LoPE was tested using EpCAM-expressing SKOV3 and OVCAR3 ovarian cancer cell lines." (PMID 34439094, 2021). "Cisplatin treatment of primary human ovarian cancer cells and the ovarian cancer cell line OVCA 433 induced EMT and CSC marker overexpression, which also included increased EpCAM expression." (PMID 34209658, 2021). "Another study that analyzed CTCs in ovarian cancer patients similarly showed that chemotherapy induced EMT changes, but EpCAM expression decreased in tested CTCs." (PMID 34209658, 2021). "Putative cell fusion-derived cancer hybrid cells co-expressing EpCAM/CD45 and CD125/CD45, respectively, were found in the ascites of ovarian carcinoma patients." (PMID 34503305, 2021). "EpCAM, claudin-4 and −7, and CD82 coexpression correlated with the metastasis and drug resistance in ovarian cancer." (PMID 32091301, 2020). "1, 2, 4, 12 and 14) further confirmed the tumor origin by cell surface staining of the ovarian cancer marker CA125 and the epithelial cell marker epithelial cell adhesion molecule (EpCAM), and intracellular staining of cytokeratin 7 (CK7)." (PMID 33346216, 2020). "With this AsiC (EpCAM-siPKCι aptamer), we achieved efficient knockdown of PKCι in ovarian cancer cells and detected dose-dependent apoptosis only in PRKCI-amplified ovarian cancer cells." (PMID 32820156, 2020). "The authors analyzed EVs derived from different ovarian cancer cell lines and found EpCAM and CD24 as markers to distinguish among ovarian cancer-derived EVs." (PMID 30872565, 2019). "By using a 3D novel engineered ExoProfile chip, diagnostic power of seven markers (EGFR, HER2, CA125, FRα, CD24, EpCAM, and CD9 plus CD63) were evaluated with AUC = 1 in ovarian cancer derived exosomes." (PMID 31718609, 2019).
ovarian carcinoma (continued). "This platform was able to efficiently capture EVs by anti-CD81 antibody and discriminate plasma EVs derived from ovarian cancer patients (n = 7) from the healthy controls (n = 5) by the mixture containing three biomarkers (CD63, CD81, and EpCAM)." (PMID 31212643, 2019). "Upregulated MDR1 in EpCAM(+)CD133(+) Huh-7 cells in the present study is also in accordance with the increased MDR1 gene expression in lung cancer, ovary cancer, osteosarcoma and glioblastoma’s cancer stem cells." (PMID 31366337, 2019). "Ovarian cancer-derived EVs carry molecules that directly regulate cancer cell migration, including CD24, EpCAM, and soluble activated leukocyte cell adhesion molecule (sALCAM) and soluble L1." (PMID 28929459, 2018). "Among the CSC markers, CD44, EpCAM, c-Kit, CD133, Oct3/4 have been shown to be abundantly expressed in ovarian carcinomas, metastatic and recurrent tumors." (PMID 29682172, 2018). "In this study, CD44, EpCAM, c-Kit and CD133 were used as CSC markers to study the responses of paclitaxel and/or momelotinib treatments in in vitro ovarian cancer cell lines." (PMID 29682172, 2018). "We found that two cancer stem cell markers, EpCAM and CD133, were expressed only in ovarian cancer cells, and the expression level of the surface marker E-cadherin was much higher in ovarian cancer cells than in cells from any of the five IHOSE cell lines." (PMID 30296284, 2018). "nPLEX has been used to differentiate ascites samples from ovarian cancer patients from healthy controls as ovarian cancer cell-derived exosomes were identified for their expression of CD24 and EpCAM." (PMID 28085080, 2017). "Using this device, they performed a multiplexed measurement of three exosomal tumor markers, including cancer antigen 125 (CA-125), epithelial cell adhesion molecule (EpCAM), and CD24, from the plasma of an ovarian cancer patient." (PMID 29258216, 2017). "EpCAM/CD3-BiTE potently killed the colon cancer cell line at a low effector-to-target ratio in vitro and significantly restricted the ovarian cancer growth in a xenograft model." (PMID 28931402, 2017). "The AdnaTest is based on the immune-magnetic isolation of ovarian cancer CTCs using antibodies against MUC1 and EpCAM." (PMID 29290959, 2017). "Recent discoveries of epithelial cell adhesion molecule (EpCAM) and CD24 in ovarian cancer-derived exosomes have been highly promising alternatives for early detection of ovarian cancer." (PMID 28851367, 2017). "In ovarian carcinomas, CD8 T cells were preferentially enriched in the stroma and rarely found in EpCAM+ tumor cell regions, as previously observed in lung tumors." (PMID 26528284, 2015). "A study showed that levels of EpCAM and CD24 present in exosomes were correlated with the aggressiveness of ovarian cancer." (PMID 25883534, 2015). "Concerning glycoproteins, exosomes derived from ovarian cancer patients carry the putative cancer marker glycosylated molecules CD24 and EpCAM, supporting their potential in diagnostics." (PMID 26248080, 2015). "In the present work, we have studied the effects of MOC31PE treatment alone and in combination with CsA on protein synthesis, cell proliferation, viability, and migration on the ovarian cancer cell lines B76 and HOC7, which both express high amounts of EpCAM." (PMID 24528603, 2014). "Recent discoveries of the presence of microRNAs, epithelial cell adhesion molecule (EpCAM) and CD24 in ovarian tumor-derived exosomes have been highly promising alternatives for early detection of ovarian cancer." (PMID 24460816, 2014). "The MOC31PE immunotoxin binds to the cell surface antigen EpCAM, which is expressed by the majority of epithelial cancers including ovarian carcinomas, and we studied the cytotoxic effects of MOC31PE in ovarian cancer cells." (PMID 24528603, 2014). "Complete elimination of EpCAM and HER-2/neu tumour cells in ascites was obtained for both ovarian cancer patients, that succumbed after 22 and 41 weeks, respectively." (PMID 22235224, 2011).
ovarian carcinoma (continued). "Two estrousregulated genes, EPCAM and KIAA0101, wereidentified in four of the five published ovarian cancer datasets and 25 geneswere identified in three out of five human studies, the majority being upregulated incancer." (PMID 21423607, 2011). "Additionally, we performed immunohistochemical analysis on clinical specimens, including 10 epithelial ovarian cancer tissue samples and 5 normal ovarian surface epithelial tissue samples, to examine MSLN and EpCAM expression patterns in tissue contexts." (PMID 40792273, 2025). "Established primary cultures were stained for ovarian cancer markers CA125, EpCam, and CD44." (PMID 38898005, 2024). "In ovarian cancer, no EpCAM overexpression was observed in 24–45% including 8–10% without EpCAM expression." (PMID 38833451, 2024). "Interestingly, phagocytic/fusion cells with the epithelial marker EpCAM and the macrophage marker CD163 were only observed in blood cells from patients with ovarian cancer." (PMID 38356723, 2024). "We observed that ovarian cancer cells were EpCam positive/CD45 negative whereas PBMCs were CD45 positive/EpCam negative." (PMID 36879003, 2023). "For instance, in the context of ovarian cancer, certain malignant cells might be proficient in the expression of mesothelin, MISIIR, and EpCAM, whereas there might be tumor cells within a given tumor site that express neither." (PMID 38146364, 2023). "Although some of the proteins identified in our ubiquitination dataset are known to be associated with ovarian cancer, such as CAP1, CRABP2, EPCAM or KRT8, their ubiquitination status has not been previously investigated in HGSC." (PMID 35292711, 2022). "One of the target pairs consists of THY1 and EPCAM, which were co-expressed on ovarian cancer cells in a subset of HGSOC but not on healthy tissue." (PMID 35115587, 2022). "As EPCAM is expressed on most epithelial cells, we searched for a second marker co-expressed on ovarian cancer cells but not on non-cancerous epithelial cells." (PMID 35115587, 2022). "By applying the fabricated microfluidics chip, they were able to detect CD24 and EpCAM in 20 ovarian cancer patient samples compared to 10 noncancer samples." (PMID 34940275, 2021). "This study has demonstrated a precision medicine-based strategy to target a subset of ovarian cancer that contains PRKCI amplification and shown that the EpCAM aptamer-delivered PKCι siRNA may be used to suppress such tumors." (PMID 32820156, 2020). "Even though previous studies have monitored specific populations of CTCs in patients with ovarian cancer, such as ERCC1, EpCAM, HE4 or Her2 positive CTCs to predict the tumor evolution and the therapy response, the biology of this circulating population is still quite unexplored." (PMID 32423054, 2020). "As EpCAM is highly expressed in ovarian cancer but not in other tissues in peritoneal cavity, we took advantage of a well characterized EpCAM aptamer as the vehicle for PKCι siRNA delivery." (PMID 32820156, 2020). "Among ovarian cancer cell subpopulations, CD83 transcript was significantly upregulated (logFC >2, p < 0.01) in EpCAM+CD45+ highly aggressive, drug-resistant, and ovarian cancer stem cell-containing tumor cells compared to EpCAM+ cells, as revealed by GSE75036." (PMID 32823589, 2020). "Finally, the DARPin strategy targeted ovarian carcinomas that express HER2/neu or/and epithelial cell adhesion molecule (EpCAM), along with EGFR-expressing glioblastomas." (PMID 33291506, 2020). "In vitro evaluation was performed using EpCAM-expressing OVCAR-3 and SKOV-3 ovarian cancer cells." (PMID 32392820, 2020). "The chip was used to detect CA125, EpCAM, and CD24 in the plasma of ovarian cancer patients." (PMID 33322519, 2020). "Lack of analysis on RAD51D, EPCAM and other essential hereditary ovarian cancer genes is another limitation of our study." (PMID 31472684, 2019).
ovarian carcinoma (continued). "Following the definition of key regulators, we could able to identify five KRs, namely, AKT1, KRAS, EPCAM, CD44 and MCAM, that are key regulators (organizers) of the ovarian cancer network." (PMID 31752757, 2019). "Furthermore, platinum-resistant ovarian cancer cells showed a higher expression of several cancer stem cell markers, such as ALDH1, CD24, and EpCAM, which are known direct targets of Wnt/β-catenin signaling." (PMID 31261739, 2019). "In ovarian cancer network, out of seventy leading hubs in the ovarian cancer network, we could able to explore five such KRs which are AKT1, CD44, MCAM, KRAS and EPCAM." (PMID 31752757, 2019). "The ovarian cancer ascites EV sample did not demonstrate a higher EpCAM concentration compared to the peritoneal fluid EV sample." (PMID 29499737, 2018). "Cells are positive for EpCAM, CK19, and CD44; they have relatively low plating efficiency/ability to form spheroids, a low migration rate, and intermediate invasiveness in matrigel, as compared to other ovarian cancer lines." (PMID 30018258, 2018). "Furthermore, the five IHOSE cell lines displayed morphological characteristics typical of epithelial cells but showed a lower level of EpCAM, CD133 and E-cadherin, as cancer stem marker, than ovarian cancer cells." (PMID 30296284, 2018). "Taken together, these results indicate that EpCAM and PI3K/Akt/mTOR targeted therapy might be promising strategies for overcoming chemoresistance in patients with ovarian cancer." (PMID 28574829, 2017). "Thus, the epithelial origin of CAISMOV24 cells was confirmed by the expression of EpCAM and PVR, two molecules expressed by ovarian epithelial cells, which are frequently overexpressed in ovarian carcinomas." (PMID 29132324, 2017). "We examined EpCAM expression in a panel of established human cell lines including lymphoma line Raji, melanoma line IGR1, colorectal cancer lines HCT8, HRT-18G, SW480, and SW620, and ovarian cancer lines PA-1, SKOV3-Luc, SW626, and CAOV-3." (PMID 28088790, 2017). "Furthermore, undetectable expression of the epithelial cell adhesion molecule (EpCAM) in normal MSC significantly increased both, at the mRNA and protein level after co-culture with different ovarian cancer cell lines such as SK-OV-3 or NIH:OVCAR-3." (PMID 27608835, 2016). "Despite some contradictory results, the observations suggest a promoting rather than a protecting role for EpCAM in ovarian cancer." (PMID 21694727, 2011). "Notably, most cells stained for EpCAM, CD44, and vimentin, suggesting that EpCAM/CD44 signals underestimate the phenotypic diversity within early passage ovarian cancer cells." (PMID 21264259, 2011). "In other types of carcinoma such as ovarian cancer, the role of EpCAM is not clear and contradictory results have been reported." (PMID 21694727, 2011). "Examples of EVs-related proteins in the context of ovarian cancer tumor biomarker detection include CD9, MUC1 (detected by aptamer-conjugated spiky Au@Fe3O4), and simultaneous detection of various markers like CD63, EpCAM, CD24, and CA-125 to avoid false positives." (PMID 40277517, 2025). "In addition, the palmitoylation of epithelial cell adhesion molecule (EpCAM) affects the formation of a complex among EpCAM, claudin isoforms, and KAI1/CD82, which is important in ovarian cancer progression, whereas 2‐BP treatment inhibits EpCAMP‐CLDN‐KAI1/CD82 complex formation." (PMID 36018061, 2023). "In addition, in ovarian cancer, AP2α, Ets1, Ets2, E2F2, E2F4, and STAT3 transcription factors have all been shown to interact with the EPCAM gene, showing some probable level of regulation of the EPCAM gene by these factors at the transcriptional level." (PMID 36230521, 2022). "EpCAM, a functional marker of ovarian cancer stem cells, forms a complex with amino acid transporters including LAT1 and CD98hc, and the expression level of LAT1 is positively correlated with poor clinical outcomes in ovarian cancer, renal cell carcinoma, and pancreatic ductal adenocarcinoma." (PMID 33401672, 2021).
ovarian carcinoma (continued). "The presence of tumor cells in these samples was confirmed by qPCR analysis of the ovarian cancer marker genes MUC16 and HE4, while five of the nineteen cell samples were additionally analyzed for cell surface expression of mucin-16 and epithelial cell adhesion molecule (EpCAM) by flow cytometry." (PMID 33584686, 2020). "For instance, miRNAs in epithelial cell adhesion molecule (EpCAM)-positive EVs could only be detected in ovarian cancer patient sera but not in normal controls." (PMID 32101583, 2020). "Coexpression of EpCAM, claudins and tetraspanin, rather than the expressions of the individual molecules at low or high levels, may be correlated with the ovarian cancer progression." (PMID 32091301, 2020). "Moreover, in the ovarian cancer EpCAM negative cells, repressive histone marker such as H3K27me3 was also found at the EpCAM gene regulatory elements." (PMID 32046162, 2020). "Furthermore, EPCAM is not expressed in healthy ovarian surface epithelium (OSE) but is frequently up regulated in ovarian cancer." (PMID 33384952, 2020). "The prognosis as a result of expression of EpCAM in ovarian cancer is not clear." (PMID 28881822, 2017). "Most studies evaluating the prognostic value of CTCs in ovarian cancer using CellSearch have reported negative results, probably owing to the low number of EpCAM-positive CTCs in ovarian cancer or the downregulation of EpCAM during the epithelial-mesenchymal transition." (PMID 29100380, 2017). "For instance, no trial has been identified to target EPCAM for ovarian cancer patients." (PMID 27801815, 2016). "Interestingly, treatment of our EpCAM-negative ovarian cancer cells with a DNA methylation inhibitor induced EpCAM expression, both on mRNA and protein level." (PMID 21694727, 2011). "Likewise, EpCAM gene over-expression was detected in the blood of neither ovarian cancer patients nor healthy females." (PMID 21129172, 2010). "However, in our study, the level of expression of EpCAM in untreated/ CoCl2 treated primary ovarian cancer cells, as well as in the CTC cultures did not increase, suggesting that a stem cell-like phenotype is being maintained by the hypoxia mimicking culture system." (PMID 36879003, 2023). "Because PCI‐1 cells express high amount of the epithelial adhesion molecule EpCAM (not shown) and the molecule has been described to be packaged into extracellular vesicles derived from ovarian cancer cells 19, we next investigated whether TEVs from PCI‐1 also contain EpCAM." (PMID 29601673, 2018). "Although both TROP-2 and EpCAM predict a poor prognosis when overexpressed in breast and ovarian cancers, in small-sized adenocarcinoma they have opposite biological effects, with TROP-2 having a negative prognostic effect while EpCAM indicating a favorable prognosis." (PMID 29989029, 2018).